ELOCP3 (elongin C pseudogene 3)
Synonyms: dJ254P11.1; formerly TCEB1P3
Gene: Processed pseudogene on chromosome 10 (10,174,230 to 10,174,577, forward strand). Ensembl gene ENSG00000229919.
Diseases named in the same sentence as ELOCP3 in open-access papers:
ELOCP3 is named in the same sentence as 1 disease in open-access papers, as found by Europe PMC text mining. Sharing a sentence is not in itself a finding about the gene and the disease.
ELOCP3 shares sentences with these, for which no sentence is quoted: cat-eye syndrome (1 paper).